EGFR (epidermal growth factor receptor)
Diseases named in the same sentence as EGFR in open-access papers (continued):
Sharing a sentence is not in itself a finding about the gene and the disease.
cholangiocarcinoma (continued). "CAR-T cells, specifically targeting the epidermal growth factor receptor, can be employed in the treatment of advanced cholangiocarcinoma cases.CD133, a recognized cancer stem cell marker, is highly expressed and linked with cancer progression." (PMID 40070825, 2025). "The Fas/FasL signaling pathway and EGFR/PI3K/Akt signaling pathway related to T lymphocytes are involved in the progression of cholangiocarcinoma." (PMID 40070825, 2025). "In this case, a 52-year-old female with cholangiocarcinoma developed LS like changes 2 weeks after her initial chimeric antigen receptor T-cell (CAR-T) infusion directed against EGFR." (PMID 39282526, 2024). "In the case of cholangiocarcinoma, EGFR and CD133 revealed synergistic effects, and the patient gained sustained disease control for thirteen months (8.5 months in PR and 4.5 months in SD)." (PMID 39835140, 2024). "Previous reports showed that GALNT5 promotes cholangiocarcinoma carcinogenesis and progression through EGFR/AKT/ERK signaling." (PMID 39433745, 2024). "The utilization of EGFR-targeting tyrosine kinase inhibitors (TKIs) has been evaluated in small phase II studies of patients with cholangiocarcinoma." (PMID 38203714, 2023). "For example, in cholangiocarcinoma, myCAF can express heparin-binding epidermal growth factor, which induces the activation of epidermal growth factor receptor in cholangiocarcinoma cells, thus promoting the migration and invasion of tumor cells." (PMID 37715019, 2023). "Of note, EGFR bypass activation has been reported as an early event in the setting of FGFR inhibition in FGFR3-altered urothelial cancer and in FGFR2-driven cholangiocarcinoma, suggesting the potential of EGFR targeting in progressive FGFR-driven diseases." (PMID 37377403, 2023). "Cytokine release syndrome was seen in only one patient with cholangiocarcinoma who received epidermal growth factor receptor (EGFR)-specific CAR-T cell therapy." (PMID 34007747, 2021). "Cytokine release syndrome was seen in only one patient with cholangiocarcinoma who received EGFR-specific CAR-T cell therapy." (PMID 34007747, 2021). "Here, we demonstrate evidence to support the use of a panel of fluorescently labeled peptides specific for EGFR, claudin-1, and ErbB2 to distinguish BilIN, the precursor lesion, and cholangiocarcinoma from normal biliary epithelium." (PMID 36345439, 2020). "Bile acids stimulate the proliferation of cholangiocytes and thereby promote cholangiocarcinoma by transactivating EGFR through a TGF-α-dependent pathway." (PMID 32365487, 2020). "A previous study demonstrated that accumulation of bile acids during cholangiocarcinoma progression leads to the activation of TGF-α/EGFR signaling." (PMID 32365487, 2020). "Experimental models have shown that bile acids can phosphorylate Epidermal Growth Factor Receptor (EGFR) in cholangiocarcinoma and immortalised cholangiocyte cell lines, leading to cell growth and proliferation." (PMID 30819129, 2019). "It has been already shown that the induction of the EGF/EGFR axis can initiate EMT in cholangiocarcinoma (CCA) cell lines and in the human embryonal rhabdomyosarcoma cell line." (PMID 31671862, 2019). "Further, a case report on a patient with advanced cholangiocarcinoma treated with anti-EGFR CART cells combined with anti-CD133 CART cells indicated the safety and feasibility of clinical cancer treatment with CSC-targeted CART cells." (PMID 28290053, 2018). "Accordingly, neutralizing antibodies that target the extracellular domain of EGFR (e.g. cetuximab) have sporadically shown clinical efficacy in advanced cholangiocarcinoma." (PMID 29666220, 2018). "There have been a couple of attempts at targeting EGFR in cholangiocarcinoma with monoclonal antibodies instead of EGFR tyrosine kinase inhibitors." (PMID 28801995, 2017). "There was a separate report treating refractory cholangiocarcinoma with sequential infusion of two different types of CAR-T cells targeting EGFR and CD133." (PMID 29058636, 2017).
cholangiocarcinoma (continued). "The EGF/EGFR axis triggers EMT in cholangiocarcinoma cells by inducing scatter of cholangiocarcinoma cells, as well as nuclear translocation of β-catenin." (PMID 27050434, 2016). "Gefitinib has been reported to be a radiosensitiser, which inhibits radiation-induced phosphorylation of EGFR and the downstream pathway and therefore enhances radiosensitivity in cholangiocarcinoma cells." (PMID 26160843, 2015). "This patient with cholangiocellular carcinoma was unmutated for EGFR exon 12 at baseline as evidenced by NGS of his primary tumor tissue (data not shown) and had stable disease after 6 months of chemotherapy in combination with panitumumab." (PMID 26059438, 2015). "LPS has recently been shown to functionally transactivate cholangiocarcinoma cell EGFR through ADAM17 (TACE)-dependent release of TGFα." (PMID 25915403, 2015). "EGFR monoclonal antibody Cetuximab plus GEMOX chemotherapy displayed a 63.0% objective response for advanced cholangiocarcinoma patients." (PMID 24303007, 2013). "We determined the gene expressions of FLT1, FLT4, HPSE, Hif1a, HB-EGF, PDGFA, PDGF-RA and EGFR in FFPE samples of patients with cholangiocarcinoma." (PMID 23704979, 2013). "EGFR and FLT1 seem to be potential markers to identify those patients at high risk of dying from cholangiocarcinoma." (PMID 23704979, 2013). "All three factors (expression of FLT1, HPSE and EGFR) were tested with ROC Analysis for their potential predictive capabilities in identifying patients with cholangiocarcinoma with a prolonged overall survival time (>3 years)." (PMID 23704979, 2013). "The significant association of high EGFR expression on survival probability and the high sensitivity and specificity of measuring EGFR expression to identify patients at risk for a shorter survival suggests that EGFR may be a useful candidate for treatment selection in cholangiocarcinomas." (PMID 23704979, 2013). "The present study sought to understand the molecular genetic characteristics of cholangiocarcinoma related to EGFR, with emphasis on its degradation and recycling." (PMID 22591401, 2012). "The combination of molecular-targeted therapy determined by the characteristics of individual EGFR phosphorylation events and EGFR recycling inhibition show promise in future treatments of cholangiocarcinoma." (PMID 22591401, 2012). "Since cholangiocarcinoma has a poor prognosis, several epidermal growth factor receptor (EGFR)-targeted therapies with antibody or small molecule inhibitor treatment have been proposed." (PMID 22591401, 2012). "All cholangiocarcinoma cell lines examined in this study expressed EGFR and VEGF, but the degree of the anti-proliferative effect of vandetanib in vitro varied between the cell lines." (PMID 19319137, 2009). "A phase II study of erlotinib, an EGFR kinase inhibitor, for advanced cholangiocarcinoma suggests the clinical benefit for EGFR inhibition in patients with cholangiocarcinoma." (PMID 19319137, 2009). "In summary, our preclinical study revealed that dual blockade of VEGFR and EGFR signalling by vandetanib resulted in considerable therapeutic effects in a mouse model of cholangiocarcinoma." (PMID 19319137, 2009). "Inhibiting both VEGFR and EGFR signalling appears a promising therapeutic approach for cholangiocarcinoma." (PMID 19319137, 2009). "Several studies have shown overexpression of EGFR, amplification and mutation of EGFR genes, and overexpression of VEGF protein in cholangiocarcinoma." (PMID 19319137, 2009). "Epidermal growth factor receptor inhibitor has been reported to be effective in a cholangiocarcinoma cell line, and a phase II study of erlotinib, an EGFR inhibitor, in patients with advanced biliary cancer has been reported." (PMID 18087285, 2008). "Notably, a cohort of cholangiocarcinoma patients demonstrated enhanced therapeutic outcomes following treatment with a composite of CAR T-cells specific to epidermal growth factor receptor (EGFR) and CD133." (PMID 38612592, 2024).
cholangiocarcinoma (continued). "In addition, deletion of LAMC2 suppressed the EMT and lymph node metastasis of cholangiocarcinoma via inactivation of the EGFR signaling pathway." (PMID 38475740, 2024). "Panitumumab, an anti-EGFR monoclonal antibody, demonstrated anti-tumor activity and tolerable safety profile in combination with gemcitabine and irinotecan in a phase II trial of patients with unresectable cholangiocarcinoma." (PMID 38203714, 2023). "In a study evaluating patient-derived models of FGFR2-fusion-positive cholangiocarcinoma, inhibition of EGFR potentiated responses to FGFR inhibitors, durably suppressing MEK/ERK and mTOR signaling, increasing apoptosis, and causing marked tumor regressions in vivo." (PMID 35444941, 2022). "For example, genistein blocks EGFR and ER to suppress cholangiocarcinoma." (PMID 35269825, 2022). "EGFR signaling plays a critical role in cholangiocarcinoma development." (PMID 32365487, 2020). "TESC was induced by TGF-α/EGFR signaling in cholangiocarcinoma." (PMID 32365487, 2020). "The epidermal growth factor receptor gene is located on chromosome 7 (7p12), and may be involved in the development of cholangiocarcinoma." (PMID 33148183, 2020). "In addition, epidermal growth factor receptor (EGFR) is activated by bile acids and has a role in the carcinogenesis of cholangiocarcinoma through the induction of cyclooxygenase-2 expression via an MAPK protein cascade." (PMID 29666220, 2018). "On the other hand, gefitinib has been reported to be a radiosensitizer, which inhibits the radiation-induced phosphorylation of epidermal growth factor receptor (EGFR) and the downstream pathway, and therefore enhances radiosensitivity in cholangiocarcinoma cells." (PMID 30563284, 2018). "In addition, a case report was published on advanced cholangiocarcinoma treated with anti-EGFR CART cells combined with anti-CD133 CART cells." (PMID 28290053, 2018). "In this study, tumor-comprising cells (i.e., vascular endothelial cells, macrophages, perihilar cholangiocarcinoma cells, and EGFR-overexpressing epidermoid cancer cells) were treated with the photosensitizer zinc phthalocyanine that was encapsulated in cationic liposomes (ZPCLs)." (PMID 27803950, 2017). "The prolonged EGFR activation results in extended ERK1/2 activation in cholangiocarcinoma cells." (PMID 26160843, 2015). "Activation of EGFR is sustained following EGF stimulation in cholangiocarcinoma cells." (PMID 26160843, 2015). "Given that i) cholangiocytes express the ERBB family members EGFR and ERBB2, and ii) previous reports demonstrated LPS-induced EGFR phosphorylation in cholangiocarcinoma, we performed western blots for phospho-EGFR or phospho-ERBB2 from 0–60 minutes post-LPS treatment." (PMID 25915403, 2015). "The significant associations of EGFR, FLT1 and HPSE gene expression with survival warrant prospective evaluation of their usability in selecting more efficient treatment strategies for patients with cholangiocarcinoma." (PMID 23704979, 2013). "However, further understanding of the mechanism of aberrant EGFR signaling is needed to refine molecular targeted therapy due to the limited response rate of cholangiocarcinoma to EGFR-targeted therapy in clinical trial." (PMID 22591401, 2012). "Bile acid mitogenesis may facilitate the progression of cholangiocarcinoma and blocking the TGF-α/EGFR autocrine pathway attenuates bile acid-stimulated growth of cholangiocarcinoma cell lines." (PMID 21087480, 2010). "On these bases, several lines of evidence may point to the usefulness of EGFR targeting as an adjuvant therapy in cholangiocarcinoma." (PMID 21087480, 2010). "The employment of targeted therapies may be useful in cholangiocarcinoma treatment and the analysis of EGFR/HER2 pathways in patients could orientate clinicians to the identification of appropriate therapeutic approach." (PMID 21087480, 2010).
cholangiocarcinoma (continued). "Collectively, targeting both angiogenesis and the active growth signal pathway, for example, inhibiting EGFR, might exert an auxiliary effect, leading to robust tumour regression in cholangiocarcinoma." (PMID 19319137, 2009). "The incidence of KRAS mutation in cholangiocarcinoma is estimated to be 54–67%, and therefore it may be important to examine the KRAS status when evaluating the activity of EGFR inhibitors in cholangiocarcinoma." (PMID 19319137, 2009). "We therefore examined whether inhibition of VEGFR and EGFR could be a potential therapeutic target for cholangiocarcinoma." (PMID 19319137, 2009). "Out of 90 cholangiocarcinoma samples, 19 (21.1%) were tested EGFR-positive by IHC." (PMID 19319137, 2009). "Collectively, the EGFR and KRAS gene status may be a potential biomarker for predicting the response to inhibitors of EGFR including vandetanib in cholangiocarcinoma." (PMID 19319137, 2009). "The absence of KRAS mutation and the presence of EGFR amplification may be potential predictive molecular marker of sensitivity to EGFR-targeted therapy in cholangiocarcinoma." (PMID 19319137, 2009). "To elucidate the biological significance and potential of these molecules as therapeutic targets, we investigated EGFR/VEGF/HER2 expression and attempted to elucidate their associations with various clinical features as well as patient survival in 236 cases of cholangiocarcinomas." (PMID 18087285, 2008). "This study suggested the clinical applicability of the EGFR inhibitor to cholangiocarcinoma." (PMID 18087285, 2008). "However, data on potential anti-EGFR therapies for cholangiocarcinoma are limited." (PMID 40732668, 2025). "A patient with advanced cholangiocarcinoma (CCA) successively received EGFR and CD133 CAR‐T cells therapy and showed a partial response (PR) continuously, which proved the feasibility of the cocktail immunotherapy." (PMID 38456710, 2024). "Sulfated galactans (SG) isolated from red alga Gracilaria fisheri have been reported to inhibit the growth of cholangiocarcinoma (CCA) cells, which was similar to the epidermal growth factor receptor (EGFR)-targeted drug, cetuximab." (PMID 33946151, 2021). "Here, we hypothesized that EGFR, claudin-1, and ErbB2 are over expressed on the cell surface in BilINs, the precursor lesion, and in cholangiocarcinoma, and can serve as targets for multiplexed imaging for future in vivo imaging to distinguish indeterminant biliary strictures." (PMID 36345439, 2020). "On this basis, this receptor in addition to a conditioning chemotherapy regimen of Cy and Nab-paclitaxel in order to eradicate stroma in other EGFR-positive solid tumors including cholangiocarcinoma (CCA) and pancreatic cancer (PC) are being tested." (PMID 28466386, 2017). "Thus, identifying more EGFR-alike molecular markers, that not only predict the prognosis more accurately but also direct therapeutic regimen selection, will be of great survival benefit for cholangiocarcinoma patients." (PMID 24303007, 2013). "This study revealed that the absence of KRAS mutation and presence of EGFR amplification may be potentially predictive molecular markers of the sensitivity of cholangiocarcinoma to EGFR-targeted therapy." (PMID 24212807, 2011). "Moreover, both the absence of KRAS mutation and the presence of EGFR amplification appear promising biomarkers for predicting the response of cholangiocarcinoma to agents that inhibit EGFR (such as vandetanib)." (PMID 19319137, 2009). "Pathogenetic studies of clinical samples revealed integrin αvβ3 cross-talked with EGFR and downstream signal transduction networks affected by thyroid hormone and EGF related to the progression of cholangiocarcinoma malignancy." (PMID 41799774, 2026). "Extrahepatic cholangiocarcinoma more commonly involves genetic abnormalities in PKA and HER2, while gallbladder cancer frequently harbors EGFR, HER2, and ERBB3 alterations." (PMID 40688855, 2025).
cholangiocarcinoma (continued). "Certainly, EGFR activation by bile acid has been shown to drive JNK activation and COX2 induction in cholangiocarcinoma cells 56 evidencing a functional connection in a liver tumour context." (PMID 38725853, 2024). "In cholangiocarcinoma, pathways like FGFR2, HER2, EGFR, VEGF, and several other signaling pathways have been targeted due to their frequent dysregulation in this cancer type." (PMID 38730642, 2024). "In addition, EGFR/HER2 inhibition by varlitinib has therapeutic effects on cholangiocarcinoma (CCA)." (PMID 37601068, 2023). "Gefitinib, an epidermal growth factor receptor (EGFR) tyrosine kinase inhibitor to enhance radiosensitivity in cholangiocarcinoma cells." (PMID 35705962, 2022). "EGFR and ErbB2 (HER2) are receptor tyrosine kinases that have been identified on comprehensive genomic profiles to be over expressed in cholangiocarcinoma." (PMID 36345439, 2020). "EGFR is aberrantly expressed or deregulated in tumors through the induction of EMT, playing crucial roles in metastatic progression, especially in cholangiocarcinoma and HCC." (PMID 27050434, 2016). "In an examination conducted using human cholangiocarcinoma cell lines, ZD6474, an inhibitor of VEGFR and EGFR signaling, showed promising anticancer activity." (PMID 24212807, 2011). "We have reported earlier that both EGFR and VEGF overexpressions are associated with progression of cholangiocarcinoma, and hypothesised that simultaneously blocking the EGFR and VEGF pathways might have synergistic therapeutic effects against cholangiocarcinoma." (PMID 19319137, 2009). "Epidermal growth factor receptor (EGFR) and vascular endothelial growth factor receptor (VEGFR) have emerged as potential therapeutic targets in cholangiocarcinoma." (PMID 19319137, 2009). "Our results suggest the validity and significance of molecular targeting agents for EGFR and/or VEGF pathway, and that further preclinical and clinical studies are warranted for improving the clinical outcome of cholangiocarcinoma." (PMID 18087285, 2008). "For instance, UDCA not only can inhibit the activation of the EGFR-ERK pathway, thereby suppressing the proliferation of cholangiocarcinoma cells, but also can inhibit the expression of PI3K and AKT, providing further evidence for its anti-tumor effects in cholangiocarcinoma cells." (PMID 39948481, 2025). "We also were unable to evaluate EGFR expression in patients without cholangiocarcinoma or in conditionally healthy individuals." (PMID 40732668, 2025). "Only one patient with BTC (EGFR amplified, KRASWT cholangiocarcinoma) achieved an unconfirmed PR, and eight patients (three KRASWT BTC, of whom one was HER2 amplified, one KRASWT PDA with HER3 protein overexpression but not HER3 amplified by NGS, three KRASMUT PDA, and one KRASMUT BTC) had SD." (PMID 40507311, 2025). "In addition, studies have discovered that cholangiocarcinoma cells overproduce mucin 1 (MUC1), which interacts with EGFR, thereby activating the EGFR/PI3K/Akt signaling pathway." (PMID 40070825, 2025). "The results showed that the SGs could inhibit the proliferation of Cholangiocarcinoma Cells (CCA), and its mechanism of inhibition was mediated by inhibited EGFR activation and the EGFR/ERK signaling pathway." (PMID 38136616, 2023). "Other targets, such as anti-angiogenesis, EGFR amp, WNT/a-catenin, Hedgehog, and HGF/c-MET, have been reported in cholangiocarcinoma, but most of these pathways can be found in most tumour types, and multiple previous clinical trials in cholangiocarcinoma have shown limited effectiveness." (PMID 36612035, 2022).